AR (androgen receptor)
Diseases named in the same sentence as AR in open-access papers (continued):
Sharing a sentence is not in itself a finding about the gene and the disease.
prostate carcinoma (continued). "These involve the dual actions of MT1 receptor-mediated down-regulation of dihydrotestosterone (DHT)-activated AR signaling, and inhibition of activated nuclear factor-kappa B (NF-κB) signaling in prostate cancer cells." (PMID 28561752, 2017). "Targeting Bag-1L and stopping it from binding to this region of the androgen receptor would represent a different approach to inhibiting the androgen receptor and treating patients with prostate cancer." (PMID 28826504, 2017). "The androgen receptor (abbreviated AR) transcription factor is a major driver of prostate cancer pathology and activated by androgen steroid hormones." (PMID 28382513, 2017). "In this study, we showed that ECI2, an enzyme involved in degradation of unsaturated lipids, is a direct AR-target and over-expressed in clinical prostate cancer." (PMID 28415728, 2017). "In the current study, we have identified ubiquitin-specific protease 14 (USP14) as a novel regulator of AR, inhibiting the degradation of AR via deubiquitinating this oncoprotein in the androgen-responsive prostate cancer cells." (PMID 28151478, 2017). "Androgen receptor (AR) signaling is one of the most critical pathways for maintaining prostate growth and normal function; however, AR activation is also important in prostate cancer pathogenesis and progression." (PMID 29170516, 2017). "R1881 also suppressed PKD1 expression in VCaP cells, a castration-resistant prostate cancer cell line that expresses wild-type AR, in a concentration-dependent manner." (PMID 28077787, 2017). "Since LNCaP cells were known AR-positive prostate cancer cells and express readily detectable PSA, we chose to use LNCaP cells as the positive control." (PMID 28903374, 2017). "Because PrKD1 down regulation in advanced prostate cancer contributes to prostate cancer progression and castration resistance by increasing AR transcriptional activity, therapeutic targeting of PrKD1 through transcriptional regulation is a novel possibility." (PMID 29108267, 2017). "To confirm whether this is also true when variants are endogenously expressed we compared two prostate cancer cell lines, LNCaP cells representing androgen sensitive early disease that express only the full length AR and CWR22Rv1 cells expressing both full length AR and AR-Vs." (PMID 27903893, 2017). "This allows us to infer that “prostate cancer”, “androgen receptor”, and “AR” are related words in their semantics." (PMID 29029598, 2017). "This current study investigates the regulatory role of androgen receptor (AR) on CXCR7 transcription in prostate cancer cells." (PMID 28596572, 2017). "Huggins and Hodges discovered in 1941 that androgens, the ligands that activate AR-FL, play a vital role in prostate cancer." (PMID 29181019, 2017). "In fact, metastatic prostate cancer cells are able to maintain AR signaling throughout this cancer development." (PMID 28262798, 2017). "Recently, the deubiquitinating enzyme USP7 has been identified as a novel AR co-regulator in prostate cancer cell." (PMID 28415632, 2017). "PARP1 plays an integral role in DNA repair, in addition, a recent report showed that PARP1 was recruited to AR binding regions and promoted AR function in advanced prostate cancer." (PMID 28264478, 2017). "Hey1 as a co-factor of androgen receptor can inhibit androgen dependent targets, including those involved in prostate cancer progression." (PMID 28915655, 2017). "Subsequently, the ligand-activated AR binds to specific DNA sequences on the target genes and initiates expression of a series of genes that promote prostate cancer progression." (PMID 28151478, 2017). "As prostate cancer is an androgen-driven disease, the high rates of androgen receptor expression found in primary and metastatic prostate tumors are not surprising, and again this study confirms that metastases retain their AR expression well." (PMID 28555048, 2017).
prostate carcinoma (continued). "Testosterone and 5α-dihyroxyltestosterone stimulate AR in prostate cancer and facilitate cancer cell growth." (PMID 28060723, 2017). "Currently, the mainstays of prostate cancer treatment are androgen ablation and/or antiandrogen treatment, which block AR signalling." (PMID 28504694, 2017). "As androgen receptor plays an important role in the pathogenesis of prostate cancer, androgen-deprivation therapy remains the principal method for treatment of patients with prostate cancer." (PMID 28783760, 2017). "A good model for investigating this is the 22Rv1 prostate cancer cell line, which expresses ARv7 protein as well as full-length AR protein." (PMID 28382513, 2017). "In the meantime, studying the role of AR and GR and their functional interactions in prostate cancer remains of major importance when developing and implementing new anti-androgen therapies." (PMID 28168446, 2017). "The biology of AR and its therapeutic importance have been investigated extensively in prostate cancer." (PMID 28957377, 2017). "Androgen receptor (AR) is a ligand-dependent transcription factor which acts as a key molecule for prostate cancer proliferation." (PMID 28587101, 2017). "It is generally known that testosterone and AR play crucial roles in prostate growth and the progress of prostate cancer." (PMID 28701750, 2017). "It has been long understood that androgen receptor signaling leads to an increase in the growth of prostate cancer cells." (PMID 28674679, 2017). "The E3 ubiquitin ligases RNF20 and RNF40 stimulate H2B ubiquitylation and AR activity at target genes, and their depletion leads to impaired prostate cancer cell proliferation." (PMID 28486411, 2017). "Mainstay treatment strategies for newly diagnosed metastatic prostate cancer exploit prostate cancer addiction to AR signaling by inhibiting the androgen/AR axis with androgen deprivation therapies (ADT)." (PMID 28152506, 2017). "The development and progression of prostate cancer is directly related to the androgen receptor (AR)." (PMID 29109383, 2017). "Compensatory mechanisms leading to increased androgen receptor expression and activity after androgen ablation or anti-androgen treatment have been identified in prostate cancer." (PMID 29214142, 2017). "The development of prostate cancer is initially driven by androgen steroid hormones via the androgen receptor (AR) transcription factor." (PMID 28701765, 2017). "Next, we demonstrated that resveratrol is capable of downregulating the levels of the endogenously expressed ARV7 as well as AR target gene mRNAs in 22RV1 prostate cancer cells." (PMID 28903374, 2017). "In the process we have screened 803 phytochemicals which can potentially act as anti-prostate cancer drugs against human AR." (PMID 28512306, 2017). "Because DDB2 reportedly promotes the ubiquitination and degradation of AR in LNCaP cell lines, we next examined the relationship between DDB2 and AR protein expression in human prostate cancer tissues." (PMID 28212551, 2017). "These genes constitute a large portion of AR-targeted genes, and some have been shown to play essential roles in prostate cancer progression." (PMID 28077787, 2017). "Various treatment options for prostate cancer, including hormone deprivation and chemotherapy, largely depend on the severity of disease, functional status, age and genetic background (e.g. androgen receptor activity)." (PMID 28830537, 2017). "Crosstalk between the androgen receptor (AR) and other signaling pathways in prostate cancer (PCa) severely affects the therapeutic outcome of hormonal therapy." (PMID 29066975, 2017). "Because of the importance of androgen and the Androgen Receptor (AR) in both development and progression of prostate cancer, existing therapy for this disease focuses on androgen deprivation or anti-androgen therapy." (PMID 28859127, 2017).
prostate carcinoma (continued). "The two AR antagonists in the treatment of prostate cancer have achieved good clinical curative efficacy, therefore they are expected to become the new drugs for the treatment of neuroblastoma in the preclinical study." (PMID 28326012, 2017). "AR is a member of the sex hormone receptor family, together with ER and PgR, and has been well studied in prostate cancer." (PMID 28060723, 2017). "The current study makes an attempt to strengthen the current understanding of prostate cancer biology with respect to AR-co-chaperones by critically dissecting its regulation and accentuating possible downstream effectors." (PMID 28852180, 2017). "The androgen receptor (AR) plays a vital role in prostate cancer, regulating a multitude of events including proliferation, apoptosis, migration, invasion, and differentiation." (PMID 28444639, 2017). "Presumably, of the various factors which lead to c-MYC gene amplification in prostate cancer, increased expression and activity of AR can increase c-Myc expression, which is a direct downstream target of AR33." (PMID 28852180, 2017). "It should be mentioned, though, that some of the effects of FK506 have been ascribed specifically to the inhibition of FKBP51, in particular by blocking the AR and thereby inhibiting prostate cancer cell growth." (PMID 29206196, 2017). "The AR has been shown to be necessary for cell proliferation, survival and invasion in early and late prostate cancer." (PMID 28420128, 2017). "The inclusion of AR evaluation should be considered, as suggested by the staining of few representative prostate cancer samples." (PMID 28415632, 2017). "In AR-negative, e.g. neuroendrocrine prostate cancer a counteraction from ERβ on AR should be obsolete." (PMID 28380417, 2017). "Here, the authors show that androgen receptor (AR) regulates HR and AR inhibition activates the PARP pathway in vivo, thus inhibition of both AR and PARP is required for effective treatment of high risk prostate cancer." (PMID 28851861, 2017). "5-α-reductase inhibitor Dutasteride, Finasteride, AR antagonist Flutamide, Bicalutamide and ER blocker Toremifene are investigated as chemoprevention agents for prostate cancer in clinical trials." (PMID 28415774, 2017). "The AR has been shown to be essential for prostate cancer cell viability, proliferation and invasion, however the mechanisms controlling this are poorly understood." (PMID 28701765, 2017). "The androgen receptor (AR) signaling pathway plays an integral role in the progression of prostate cancer." (PMID 28264478, 2017). "Meta-analysis results of association between androgen receptor CAG polymorphism and prostate cancer risk." (PMID 28640128, 2017). "In contrast to the majority of previous reports suggesting tumor suppressive functions in other cancers, our observations identify a clear oncogenic role for ING3, which acts as a co-activator of AR in prostate cancer." (PMID 28511652, 2017). "Studies with AR in prostate cancer suggest that the AR cistrome is broadly reprogrammed during tumorigenesis, supporting a model in which nuclear receptors take on de novo target regulation in transformed cells." (PMID 29143738, 2017). "Androgen and AR-mediated signaling are therefore crucial for the development and functioning of both the normal prostate and prostate cancer." (PMID 28286531, 2017). "Our studies also revealed that reducing AR-FL expression by siRNA-mediated knockdown enhanced the ability of rosiglitazone to suppress proliferation of C4-2 prostate cancer cells." (PMID 29181019, 2017). "Analysis of ~150 castration-resistant prostate cancer metastases revealed that SLC35F2 expression correlated with AR activity score, but that a subset of patient tumors had high expression of the transporter regardless of AR status." (PMID 28350329, 2017). "Overactive AR signaling is an important oncogenic driver in several tumor types, including prostate cancer and a subset of breast cancers." (PMID 28208703, 2017).
prostate carcinoma (continued). "Together, these findings suggest that the expression of AURKA is regulated by androgen in prostate cancer cells that highly express AR, emphasizing its potential as a therapeutic target in patients with CRPC." (PMID 29269934, 2017). "AR is targeted by anti-androgenic therapies used for the treatment of prostate cancer and in tumors cooperates with HOXB13, a gene that when mutated causes predisposition to prostate cancer." (PMID 29312534, 2017). "Prostate cancer is typically androgen-dependent during its initial stages when the hormone androgen binds to the androgen receptor (AR) and then transactivates target genes." (PMID 28286531, 2017). "Androgen receptor (AR) is a validated drug target for prostate cancer based on its role in proliferation, survival, and metastases of prostate cancer cells." (PMID 28144231, 2017). "In this review, we summarize the AR signaling pathway in terms of AR collaborators and focus on pyrrole-imidazole (PI) polyamide as a candidate compound for the treatment of prostate cancer." (PMID 28264478, 2017). "Although identified on AR-positive LNCaP cells, binding sites for 2-[125I]-melatonin were undetectable on the membrane of AR-negative prostate cancer cells such as PC3 and DU145." (PMID 28420185, 2017). "Down-regulation of androgen receptor (AR) and cell proliferation regulator E2F-1 was indicated as the mechanism behind thymoquinone's action in prostate cancer." (PMID 28881699, 2017). "The primary therapeutic strategy for advanced prostate cancer treatment is to block androgen signalling through androgen deprivation therapy or AR blockade, thereby halting tumour progression." (PMID 28382513, 2017). "Multiple reports have shown that treatment of human prostate cancer cells with PPARγ ligands alters AR signaling." (PMID 29181019, 2017). "Previous experiments demonstrated that the transcriptional amplification system PSEBC-TSTA-fl is able to specifically quantify androgen receptor (AR) activity modulation in vitro and in vivo in prostate cancer cells." (PMID 28182747, 2017). "Metastatic PrCa is treated with androgen deprivation therapy (ADT) because most prostate cancers require androgen receptor (AR) signaling to maintain growth and viability." (PMID 29100379, 2017). "In advanced prostate cancer, loss of STAT1 expression is a poor prognostic factor, particularly in a subgroup of patients with low nuclear androgen receptor expression." (PMID 28881828, 2017). "This study provides further evidence for the significance of androgen receptor signalling in the progression of prostate cancer." (PMID 27902483, 2017). "The PI3K/AKT/mTOR and the Androgen Receptor signalling pathways are important drivers of prostate cancer growth and progression." (PMID 28915623, 2017). "Androgen receptor (AR) plays a critical role in the development of prostate cancer and androgen deprivation therapy (ADT) is the first line therapy for newly diagnosed prostate cancer patients." (PMID 28410242, 2017). "CtBP2 was originally investigated in the context of prostate cancer, and recent reports indicate that CtBP2 can modulate androgen receptor activity to promote prostate cancer progression." (PMID 28404932, 2017). "Benign human prostate organoids were transduced with lentiviruses expressing MYC, shPTEN, shTP53 and AR, alone and in various combinations, to recapitulate prostate cancer development." (PMID 28881646, 2017). "Previous studies showed that SPOP inactivation increased cell proliferation primarily in AR-positive prostate cancer cells, but increased prostate cell migration and invasion in an AR-independent manner." (PMID 28448495, 2017). "Androgen receptor (AR) activation is the primary driving factor in prostate cancer which is initially responsive to castration but then becomes resistant (castration-resistant prostate cancer (CRPC))." (PMID 28717648, 2017).
prostate carcinoma (continued). "In recent years, investigations of ubiquitin ligase E3 have highlighted them to be pivotal regulators of AR transcription activity in prostate cancer." (PMID 28549433, 2017). "During progression to an androgen-independent state, prostate cancer cells continue to express the androgen receptor (AR) and androgen-regulated genes, indicating that AR is critical for the proliferation of castration-resistant prostate cancer (CRPC) cells." (PMID 28671964, 2017). "The progression of prostate cancer is mainly influenced by androgens and the androgen receptor (AR)." (PMID 28264478, 2017). "RNF6 is involved in prostate cancer progression by mediating the K63-chain ubiquitination on androgen receptor thus modulating AR transcriptional activity and specificity." (PMID 28223545, 2017). "Correlations between AR expression and clinicopathologic variables were analyzed in 640 prostate cancer patients." (PMID 28262798, 2017). "Targeting the activation function-1 (AF-1) domain located in the N-terminus of the androgen receptor (AR) is an attractive therapeutic alternative to the current approaches to inhibit AR action in prostate cancer (PCa)." (PMID 28826504, 2017). "The androgen receptor (AR) plays important roles in prostate cancer development and prostate tumor growth." (PMID 28783103, 2017). "Although AR was reported to be downregulated by sorafenib treatment in HCC24 and prostate cancer, the underlying mechanism how sorafenib decreases AR still remained elusive." (PMID 29022906, 2017). "Wedelia chinensis is rich in luteolin, apigenin, and wedelolactone that act synergistically to suppress androgen receptor activity in prostate cancer." (PMID 29142311, 2017). "RAB3B, up-regulated in prostate cancer through AR, was the top-most jointly differentially expressed gene in this subgroup, with reduced expression relative to either NEPCs or adenocarcinomas." (PMID 29132337, 2017). "The first systematic discovery of genomic AR binding sites was based on ChIP-on-chip and ChIP-seq experiments on AR-positive prostate cancer cell lines." (PMID 28168446, 2017). "Here we investigate the effect of simultaneous inhibition of the aryl hydrocarbon receptor (AhR) and Src on androgen receptor (AR) signaling in prostate cancer cells." (PMID 28671964, 2017). "There are multiple lines of evidence shown that RSV exerts its effects on prostate cancer in an AR-dependent manner through involvement of the regulation of AR expression and function." (PMID 28903374, 2017). "TNBC subtypes showed differential sensitivities to cisplatin, bicalutamide (an androgen receptor antagonist used in prostate cancer), and PI3K/mTOR inhibition." (PMID 29108347, 2017). "The AR is also involved in the development of prostate cancer (PCa) and current treatments for metastatic disease are based on the inhibition of androgen signaling pathways." (PMID 29069764, 2017). "The NRs in the cancer group include RARA (acute promyelocytic leukemia), NR1H4 (hepatocellular carcinoma), ESR1 (breast cancer), and AR (prostate cancer)." (PMID 29065888, 2017). "In this review, we examine how AR and PPARγ each regulate the growth and development of normal prostatic epithelial cells and prostate cancers." (PMID 29181019, 2017). "For example, when overexpressed in cancers derived from basal epithelial cells, the AR functions as a tumor suppressor to inhibit the proliferation of basal cells and drive them into differentiation, resulting in the inhibition of prostate cancer metastasis." (PMID 28212551, 2017). "Here we demonstrate a direct requirement for the androgen receptor (AR) to maintain HR gene expression and HR activity in prostate cancer." (PMID 28851861, 2017). "The antiandrogens, such as bicalutamide, targeting the androgen receptor (AR), are the main endocrine therapies for prostate cancer (PCa)." (PMID 28293633, 2017).